CXCR4 (C-X-C motif chemokine receptor 4)
Diseases named in the same sentence as CXCR4 in open-access papers (continued):
Sharing a sentence is not in itself a finding about the gene and the disease.
cancer (continued). "High plasmacytoid dendritic cells could promote the expression of CXCR4 by TNF-α/NF-κB pathway, and blocking CXCR4 could effectively inhibit cancer progression and enhanced the curative effect of immune checkpoint blockers by up-regulating Treg cells infiltration." (PMID 33324682, 2020). "Here, targeting the mTOR pathway may prevent cancer metastasis driven by CXCL12/CXCR4 interaction." (PMID 32483450, 2020). "We have discussed several reports showing that CXCR4 can control cell proliferation in addition to directing cell retention and movement, both in physiological processes, such as development and tissue regeneration, and in pathological ones, such as cancer growth." (PMID 32983169, 2020). "Notably, these observations may explain that while CXCR4 overexpression is highly correlated with cancer metastasis and mortality, plasma membrane localization is not." (PMID 33339901, 2020). "This downregulation of CXCR4 expression could also inhibit the distant metastasis of cancer." (PMID 33195200, 2020). "Furthermore, high concentrations of CXCL12 are present at the common sites of metastases, suggesting that CXCL12/CXCR4 signaling may have a role in the homing of cancer cells to distant organs." (PMID 32224910, 2020). "The chemotactic effect on multiple cell lines by CXCL12 and its receptors might indicate the global importance of CXCL12/CXCR4, 7 chemokine axis in the modulation of cell migration and mediates cross‐talk as well as the interaction between immune and cancer cells." (PMID 29105376, 2018). "Biotherapies that target CXCR4-overexpressing cancer cells may be feasible." (PMID 29686536, 2018). "In addition, high CXCR4 expression is observed in a variety of cancers." (PMID 29636841, 2018). "Thus, targeting the CXCR4/CXCL12 may provide a dual benefit of inhibiting cancer cell migration and lymphangiogenesis to curb lymphatic metastasis." (PMID 29527513, 2018). "Therefore, the complex and cell-specific regulation of CXCR4 by CXCR7 may explain the different effects of CXCR7 overexpression by having a differential regulation of the CXCR4-CXL12 axis depending on the cancer type." (PMID 29920526, 2018). "Moreover, combinatorial treatment of conventional chemotherapy with CXCR4 inhibitors might be an approach to overcome cancer therapy resistance." (PMID 30622535, 2018). "We expected this regime to maintain sufficiently low the fraction of CXCR4+ cancer cells remaining in primary tumors and metastatic foci, along the treatment period, as to efficiently block metastasis and/or foci growth, provided that CXCR4+ cancer cells act as MetSCs." (PMID 30190334, 2018). "Additionally, inhibiting the activity of SDF-1 or blocking its binding to CXCR4 could reduce the migration or metastasis of cancer cells." (PMID 28067275, 2017). "Likewise, CXCR4 expression was detected up-regulated upon hypoxia, which is one of the main microenvironmental conditions involved in the activation of a compensatory angiogenic response in cancer." (PMID 29240722, 2017). "Down-regulation of the chemokine CXCR4 gene, known to be involved in cisplatin resistance, dissemination of peritoneal metastasis and development of cancer-initiating cells in several cancer, including EOC, was another special feature of OSPC2 cells induced by FOXM1 loss." (PMID 28482906, 2017). "Therefore, we hypothesized that mifepristone may suppress the expression and function of SDF-1/CXCR4 signaling axis, and further interfere this chemokine axis with concomitant inhibition of cancer metastasis." (PMID 28938623, 2017). "The PI3K pathway has been described in several studies to regulate glucose metabolism in cancer, thus our findings on inhibitory effects on CXCR4 expression and EGFR activation/expression could be involved in the reduction of glycolytic flux by the inhibition of PI3K/AKT axis." (PMID 28423060, 2017). "Furthermore, senescent cells increase the survival of cancer cells via CXCL12/CXCR4 signalling." (PMID 28489070, 2017).
cancer (continued). "The reduction in cell viability induced by MIR494 has been observed in other cancer types; indeed, several MIR494 targets have been thus far identified which are associated with reduced cellular survival including IGF2, c-KIT, HOXA10, CLPTM1L, SCGN, CXCR4, and c-myc." (PMID 26794413, 2016). "Our results, which identify CXCR4 as an important gatekeeper of keratinocyte proliferation and as a new susceptibility factor in HPV pathogenesis, may be translated into anti-viral and anti-cancer strategies." (PMID 27918748, 2016). "In addition, a report suggested a relationship between CXCR4 and cancer stem cells." (PMID 27175473, 2016). "Indeed, these tissues tend to be the metastatic sites of CXCR4-high cancer cells." (PMID 26993780, 2016). "Thus, AMD3100 may ultimately improve the outcome of SCLC patients and also be of important value in a wide range of CXCR4-expressing cancers." (PMID 27835905, 2016). "CXCR4 is one of the most common chemokine receptor that has been demonstrated to be over expressed in human cancers, while its expression is low or absent in many normal tissues, including breast, emphasizing a critical role for this chemokine receptor in modulating cancer cell behavior." (PMID 27556298, 2016). "Moreover, the CXCR4/CXCL12 axis seems to be tightly linked to the immune checkpoint regulator programmed death 1 (PD-1) and programmed death-ligand 1 (PD-L1) that co-operate to suppress anti-cancer immunity." (PMID 27462860, 2016). "We were also interested in the effect of autophagic inhibition on reported virulent transformation markers, such as CXCR4, SOX9, and CD44, and on chemokines, such as CXCL1 and IL8, since various reports have indicated that these markers and inflammation are associated with cancer initiation." (PMID 26496833, 2015). "Furthermore, CXCR4 is the chemokine receptor most widely expressed in malignant tumors." (PMID 26347749, 2015). "Finally, our finding that dormant cancer cells express a low level of CXCR4 suggests that treatments targeting the CXCL12-induced CXCR4-mediated signaling may be ineffective for cells at this stage." (PMID 26083776, 2015). "Therefore, understanding the function of CXCR4 may provide new insights for the development of novel therapeutic strategies for the treatment of cancer." (PMID 26622806, 2015). "In addition to CXCR4-dependent mechanisms other signals are likely to contribute to the cancer cell proliferation induced by the PSC–CCM due to that AMD3100 could only partially antagonize this proliferation promoting effect." (PMID 26010611, 2015). "Furthermore, it is unclear whether HSA cells create CXCL12-enriched environments that affect CXCR4-expressing cancer cells, or whether these CXCR4-expressing cells migrate to and/or colonize organs and tissues where there is abundant CXLC12." (PMID 29061949, 2015). "CXCL12/CXCR4 is a critical signaling pathway in the regulation of leukocyte recruitment and embryo development and has recently been demonstrated to play important roles in cancer invasion, metastasis, angiogenesis, cancer cell-microenvironment interaction and chemoresistance." (PMID 25679210, 2015). "In addition, tumor-initiating cells from some brain cancer cell lines may preferentially express CXCR4, contrasting with more differentiated cancer cells with greater expression of CXCR7." (PMID 24896823, 2014). "This is similar to previous reports that CXCR4 may be a useful marker for cancer progression." (PMID 25471741, 2014). "In addition, CXCR4 positive cancer cells can be recruited to CXCL12-rich mesenchymal stroma niches." (PMID 25471741, 2014). "Because the SDF-1/CXCR4/CXCR7 axis plays a critical role in cancer development, progress, metastasis and recurrence, we hypothesize that SDF-1 and its receptors CXCR4 and CXCR7 might also be connected with the outcome of treatment of endometrial cancerpatients." (PMID 24416254, 2014). "The results may provide a basis for cancer therapy which targets CXCR4." (PMID 25202367, 2014).
cancer (continued). "To investigate the relationships of cancer-associated fibroblasts (CAFs) and related molecules to neoangiogenesis, we performed immunohistochemical analyses of alpha-smooth-muscle actin (α-SMA), stroma-derived factor-1 (SDF-1), and its cognate receptor CXCR4 in primary NPC lesions." (PMID 24877105, 2014). "Based on the well-characterized roles of CXCL12 and CXCR4 in chemotaxis and the similarities between chemotactic cell migration and cancer cell movement to distant sites, this receptor-ligand pair has been hypothesized to play a role in cancer pathogenesis and metastasis." (PMID 23322021, 2013). "Moreover, CXCR4 has been detected in the nucleus of several cancer tissues." (PMID 23468933, 2013). "Thus, targeting of CXCR4 by an appropriate therapeutic agent may be a means of controlling the aggressiveness of cancers." (PMID 25285238, 2013). "Furthermore, our aim was to determine (i) the specificity of this process for carcinoma cells, (ii) the potential involvement of cells other than microglia, and (iii) the role of CXCR4 as well as (iv) to investigate essential WNT signaling contributions during this process in more detail." (PMID 23832647, 2013). "Furthermore, we found that treatment with SDF-1 could further induce the occurrence of EMT in CD133+CXCR4+ cancer cells." (PMID 22871210, 2012). "Moreover, a prior report showed that NF-κB could promote migration and organ-specific homing of cancer cells through the induction of CXCR4." (PMID 22200669, 2012). "The role of CXCR4 in cancer depends on whether it is in an activated signaling state." (PMID 22242160, 2012). "In addition SDF-1/CXCR4 in malignant tumors could provide paracrine signals that promote malignant progression, i.e. invasion and cell proliferation that leads to metastasis." (PMID 22709548, 2012). "However, in our previous study, we found that CXCR4 nuclear localization may be responsible for certain metastatic changes in cancer cells." (PMID 23039915, 2012). "Furthermore, Treg recruitment by CXCL12/CXCR4 in these cancers may potentially be modulated by treatment directed against the HIF-1α pathway." (PMID 21521526, 2011). "The CXCL12/CXCR4 signaling axis has been implicated in both cancer metastases and human immunodeficiency virus type 1 (HIV-1) infection and a more complete understanding of CXCL12/CXCR4 signaling pathways may support efforts to develop therapeutics for these diseases." (PMID 21949786, 2011). "Further, osteopontin and CXCR4 may serve as early biomarkers for cancer detection." (PMID 21909361, 2011). "Continued studies of molecular interactions, of patients with malignancies, and of populations at risk for these diseases are needed to develop insight into the roles of CXCR4 in breast and other cancers, which may lead to new approaches for prevention or treatment." (PMID 21179547, 2010). "Although nuclear CXCR4 is expressed in cancer cells, its function remains unclear." (PMID 20181250, 2010). "Hence, CD133+CXCR4+ cancer cells might acquire a migratory phenotype during the EMT process and therefore are involved in invasion and metastases to distant sites." (PMID 24281178, 2010). "Thus, SDF-1 secreted by mammary myofibroblasts may stimulate the growth of CXCR4-expressing carcinoma cells as well as angiogenesis." (PMID 20822533, 2010). "It has been suggested that ligand-receptor interaction and subsequent activation of the SDF-1α/CXCR4 complex may preferentially arrest cancer cells in the vascular beds of SDF-1α−expressing organs and could contribute to metastatic homing and invasion of these cells in such specific organs." (PMID 19325708, 2009). "Since CXCR4 and CXCL12 are implicated in theprogression of many different cancers, it is of interest to determine whetherDIM and/or genistein downregulate these proteins in cancer cell lines of otherorigins." (PMID 19325924, 2009). "NO may play an important role in metastasis of this cancer via CXCR4 induction." (PMID 18826577, 2008).
cancer (continued). "Thus, a controlled release of CXCR4 antagonists might lead to effective suppression of cancer metastasis." (PMID 19787093, 2008). "Although nuclear CXCR4 expression occurs in normal and cancer tissues, its function is unknown." (PMID 19025611, 2008). "Thus, cytoplasmic CXCR4 expression in cancer cells may be more important for migration of cancer cells, leading in turn to lymph node metastasis and poor prognosis." (PMID 19025611, 2008). "However, CXCR4 appears to be the major chemokine receptor expressed on cancer cells." (PMID 17083723, 2006). "Migrating cancer stem cells (miCSCs), marked by CD133+CXCR4+ expression is a key driver of PDAC progression, which currently lack effective therapeutic targets." (PMID 41991735, 2026). "In cancer-derived MDA-MB-231 cells, CXCR4 and CCR5 formed stable, slow-diffusing higher-order assemblies, whereas in COS7, HEK293, and MCF-10A cells the receptors were detected mainly as weaker monomer-dimer mixtures." (PMID 42239782, 2026). "CXCR4 is a G-protein-coupled receptor (GPCR) expressed on lymphocytes, endothelial cells, hematopoietic stem cells, stromal fibroblasts, and cancer cells." (PMID 40868199, 2025). "In a meta-analysis study, it was found that CXCR4 was more highly expressed in NSCLC than normal tissue, its expression was higher in later stage cancers as well as in metastatic NSCLC." (PMID 39982274, 2025). "Maximum of the cancers displayed the pattern, with enhanced expression of IL19, TGFβ-1, CXCR4, BMP1, VCAN, and WNT2 protein levels in the samples of KICH, KIRC, LUAD, LUSC especially BRCA when compared to normal samples." (PMID 41348904, 2025). "For example, the CXCR4-antagonist peptide E5 has been used to target PEG-PE copolymer nanoparticles or DSPE-mPEG2000 micelles to CXCR4+cancer cells." (PMID 40307933, 2025). "Immune-modulating proteins such as CXCR4, CD40, IL7R, TGFBR1, and SEMA4D are frequently targeted for cancer intervention studies." (PMID 40805206, 2025). "The results demonstrated that cancer cells interact with stromal cells via the PTN-NCL and MIF-(CD74+CXCR4) signaling pathways." (PMID 40642071, 2025). "Cancer cells induce a TGF-β-dependent increase in CXCR4 levels in monocytes, and CXCL12 expressed by perivascular fibroblasts attracts these mobile TAMs to blood vessels, entrapping mobile cancer cells." (PMID 40427136, 2025). "Our findings demonstrate that inhibition of CXCR4 suppresses bone invasion by OSCC through dual mechanisms: inhibiting osteoclast activation and impairing the EMT process in cancer cells." (PMID 41413548, 2025). "This study used exosomes modified with C-X-C chemokine receptor type 4 (CXCR4) and TNF-related apoptosis-inducing ligand (TRAIL) to target cancer cells." (PMID 40533746, 2025). "The bar charts show the total alteration frequency of six hub genes (CD36, CXCL12, CXCR4, CYBB, ITGAM, PLEK) in pan-cancer." (PMID 40895569, 2025). "Within this complex network, the chemokine receptors CXCR4 and CXCR7 emerge as critical regulators of cancer progression and metastasis, primarily through β-arrestin-dependent signaling cascades." (PMID 40143176, 2025). "Canonical pathway analysis revealed significant inhibition of several cancer-related pathways, including ERK/MAPK, phosphoinositide 3-kinase (PI3K)/AKT, and CXCR4 signaling." (PMID 40167359, 2025). "In neuroblastoma, SOX17 inhibited cancer cell proliferation and invasion through the CXCL12/CXCR4 signaling axis." (PMID 40909292, 2025). "CQ has been shown to inhibit the TLR9/nuclear factor kappa B signaling pathway, thereby reducing cancer invasiveness, and both CQ and HCQ can suppress cancer cell proliferation by interfering with the CXCL12/CXCR4 signaling pathway." (PMID 40805187, 2025). "The activation of CXCR4 and the migration of cancer cells towards organs that express CXCL12 facilitate the directed metastasis of cancer cells." (PMID 40923371, 2025).
cancer (continued). "Functional assays, including wound healing and cell migration assays, were conducted across various cell types, including CD4+ T cells and cancer cells, to evaluate the impact of GPR15LG on CXCL12-mediated CXCR4 signaling." (PMID 40394646, 2025). "For instance, salivary adenoid cystic carcinoma cells had increased expression of CXCL12 and CXCR4, enhanced invasion, and metastasis after overexpression of NR2F1; knockdown of NR2F1 reduced the invasive phenotype in these cancer cells." (PMID 40955663, 2025). "In the context of cancer, the chemokine receptors CCR4 and CXCR4 have been extensively investigated." (PMID 41346591, 2025). "Neutrophils are polarized to the N2 TAN phenotype via Notch2–Jagged1 interaction of cancer cells and CAFs, accompanied by increased expression of ARG, C-C motif chemokine ligand 2 (CCL2), CXCR4 and MMP-9." (PMID 41429896, 2025). "Meanwhile, CXCR4 directs CSCs to metastatic sites by interacting with SDF1, promoting cancer spread." (PMID 40422220, 2025). "C-X-C chemokine receptor type 4 (CXCR4) plays a critical role in immune cell trafficking and cancer metastasis." (PMID 40394646, 2025). "amalgamated single‐cell RNA sequencing data from 575 patients with cancer to establish a comprehensive pan cancer EC atlas and discovered two notable subpopulations: SELE+ veins and CXCR4+ tip cells." (PMID 40268524, 2025). "Agonist-dependent activation of CXCR4 and CB2 results in reduced expression of phosphorylated ERK1/2 mediated by CXCR4 and ultimately reduced cancer cell functions such as calcium mobilization and cell chemotaxis." (PMID 41347146, 2025). "Key molecules for cancer progression were inhibited (IL6, IL4, CXCL8, CXCR4, CXCL12; ICAM1, CD44 and BCL2), and pro-apoptotic BAD was activated." (PMID 41595551, 2025). "CXCL12 and its receptors, CXCR4 and CXCR7, are commonly found in high levels in various cancers, including BLCA." (PMID 40918470, 2025). "In the co-culture system of T cells, CAFs, and cancer cells, a greater number of T cells adhered to CAFs when co-cultured with RCM-SO, and this adhesion was reduced by CXCR4 inhibition." (PMID 40849508, 2025). "This review explores how the chemokine receptor type 4 (CXCR4/CXCL12) axis facilitates drug resistance through mechanisms such as epithelial–mesenchymal transition (EMT), cancer stemness, and microenvironmental interactions." (PMID 41002447, 2025). "The study also proposes disrupting the heterocomplex as a potential therapeutic target to inhibit cancer invasion and metastasis, emphasizing the important roles of CXCL12 and CXCR4 in this process." (PMID 41347146, 2025). "Monoclonal antibodies (mAbs) targeting CXCR4 have shown promising results in both solid tumors and hematological malignancies by blocking the CXCR4/CXCL12 axis and inducing cancer apoptosis." (PMID 40307933, 2025). "ACCEPT software was indicatively used to automatically identify cancer cells, providing simultaneous information regarding the expression level (intensity) of JUNB and CXCR4." (PMID 39575761, 2025). "Here, we examined the interactions of GPR15LG with CXCR4 and ACKR3 and their consequences on downstream signaling as well as immune and cancer cell trafficking." (PMID 40394646, 2025). "To support their possible roles in crucial oncogenic mechanisms, we assessed the mutation frequency, copy number amplification, and copy number–expression correlation of STC2, MIF, CD74, CXCR4, GDF15, and TGFBR2 across several cancer types." (PMID 41502509, 2025). "Specifically, GPR15LG enhances CXCL12-mediated CXCR4 signaling synergistically, promoting wound healing and cell migration across various cell types, including CD4 + T cells and cancer cells." (PMID 40394646, 2025). "While CXCR4 and S1P1 are coexpressed in cancer and immune cells and participate in overlapping processes, their interaction remains complex." (PMID 40012038, 2025).